PDGFRA (platelet derived growth factor receptor alpha)
Diseases named in the same sentence as PDGFRA in open-access papers (continued):
Sharing a sentence is not in itself a finding about the gene and the disease.
lymphoid neoplasm (40 papers, 2009 to 2025). A neoplasm composed of a lymphocytic cell population which is usually malignant (clonal) by molecular genetic and/or immunophenotypic analysis. "Examples include chronic inflammatory reaction, post chemotherapy setting, and myeloid/lymphoid neoplasms associated with PDGFRA rearrangement." (PMID 38067330, 2023). "Myeloid/lymphoid neoplasms with platelet-derived growth factor receptor alpha (PDGFRA) rearrangements are the most frequent of these disorders and are usually present in adult males with a median age of the late 40s." (PMID 36589160, 2022). "We present our diagnostic and management approach of this patient and review prior relevant pediatric cases of myeloid/lymphoid neoplasms with PDGFRA rearrangement." (PMID 36589160, 2022). "In two other cases (20%), a FIP1L1-PDGFRA fusion was detected, which established the diagnosis of myeloid/lymphoid neoplasms with PDGFRA rearrangement according to the WHO 2016 classification." (PMID 35454892, 2022). "Mastocytoses were also listed within the spectrum of MPNs, while myeloid/lymphoid neoplasms with PDGFRA, PDGFRB, and FGFR1 rearrangements were considered separately." (PMID 34830822, 2021). "Therefore, this disease belongs to the new WHO category of myeloid and lymphoid neoplasms with abnormalities in PDGFRA, PDGFRB and FGFR1 genes." (PMID 22356850, 2012). "The current 2017 WHO classification recognizes the following specific diseases: M/LNs-Eo with rearrangements of PDGFRA, PDGFRB and FGFR1 respectively and the provisional entity of myeloid/lymphoid neoplasms with PCM1-JAK2 rearrangement." (PMID 34205834, 2021). "By definition, there should be no Philadelphia chromosomeor a rearrangement involving PDGFRA/B andFGFR12.The second group falls under the category of myeloid/lymphoid neoplasms witheosinophilia and rearrangement of PDGFRA, PDGFRB,or FGFR1, or with PCM1-JAK2." (PMID 30241197, 2018). "While these reports revealed it is not uncommon for PDGFRA and FGFR1 genetically rearranged cells to differentiate into lymphoid neoplasms, hematologic diseases bearing PDGFRB mutations are rare." (PMID 22356850, 2012).
mesenchymal tumors (38 papers, 2007 to 2026). "GISTs are mesenchymal tumors that display constitutive activation of KIT or PDGFRA through gene mutations, which can predict the response to imatinib-based therapy." (PMID 37907993, 2023). "GISTs, the most common soft tissue sarcomas of the GI tract, most commonly contain KIT- or PDGFRA-activating mutations and are derived from mesenchymal neoplasms in the GI tract." (PMID 35672812, 2022). "GIST is a mesenchymal tumor based on the carcinogenic mutation of the stem cell factor receptor (KIT) or the platelet-derived growth factor receptor alpha (PDGFRA) gene, which can be treated with a tyrosine kinase inhibitor (TKI), such as imatinib." (PMID 33681289, 2021). "KIT and PDGFRA mutations drive mesenchymal tumors, including GISTs (gastrointestinal tract sarcomas)." (PMID 23420084, 2013). "It is widely accepted that a GIST is a mesenchymal tumor that expresses the c-kit oncoprotein or has a mutation in either the c-kit or the platelet-derived growth factor receptor-alfa (PDGFRA) gene." (PMID 17540038, 2007). "In stark contrast, GIST, the most common mesenchymal tumor of the gastrointestinal tract, arises from Cajal interstitial cells and characteristically harbors KIT or PDGFRA mutations." (PMID 41488102, 2025). "GISTs are the most common mesenchymal tumors of the gastrointestinal tract, with a distinctive molecular pathogenesis, primarily driven by mutations in the KIT or PDGFRA genes." (PMID 39559661, 2024). "The results indicated that PDGFRA-mutant GISTs should be considered a differential diagnosis when encountering an ALK-positive mesenchymal tumor, especially those with CD117-negative or weakly positive in immunohistochemical staining." (PMID 37120571, 2023). "GISTs, mostly caused by mutations in the PDGFRA and KIT genes, are the most common mesenchymal tumor in the gastrointestinal tract." (PMID 30653164, 2019). "GISTs are the most common mesenchymal tumor in the gastrointestinal tract, the most common of which are KIT or PDGFRα activation mutations." (PMID 27845908, 2017). "The status of PDGFRα in PEComa should be further studied to diagnose PDGFRα-positive mesenchymal tumors in the gastrointestinal tract." (PMID 27842558, 2016). "PEComa should be included in the differential diagnosis of mesenchymal tumors in the wall of the gastrointestine, even though tumor cells are immunohistochemically PDGFRα-positive." (PMID 27842558, 2016). "GISTs are the most common mesenchymal tumors of the gastrointestinal tract, typically arising in the stomach and small intestine, and are characterized by activating mutations in KIT or PDGFRA, which play a central role in tumorigenesis and therapeutic response." (PMID 40703587, 2025). "The benefit of evaluating metabolic response using [18F]FDG PET/CT is well demonstrated in KIT- or PDGFRA- mutated GIST tumours following treatment with the tyrosine kinase inhibitor; imatinib, as mesenchymal tumours such as GIST rarely demonstrate a reduction in size despite therapeutic response." (PMID 33443647, 2021). "Our study revealed 7.7% (4/52) of ALK expression in PDGFRA-mutant GISTs, indicating that molecular tests were required to rule out the possibility of PDGFRA-mutant GISTs when encountering ALK-positive mesenchymal tumors with CD117-negative or weakly positive in immunohistochemical staining." (PMID 37120571, 2023). "The utility of PDGFRA mutation testing to confirm the diagnosis of IFP is minimal, but it is important to realize that not all PDGFRA-mutated mesenchymal neoplasms in the GI tract are GISTs." (PMID 21403834, 2011).
hypereosinophilic syndrome (37 papers, 2009 to 2026). Hypereosinophilic syndrome (HES) constitutes a rare and heterogeneous group of disorders, defined as persistent and marked blood eosinophilia and/or tissue eosinophilia associated with a wide range of clinical manifestations reflecting eosinophil-induced tissue/organ damage. "The presence of the Fip1-Like1-platelet-derived growth factor receptor alpha (FIP1L1-PDGFRα) fusion gene is a rare cause of hypereosinophilic syndrome requiring a distinct therapeutic approach." (PMID 42130655, 2026). "Mutations in FIP1L1-PDGFRα (FIP1-Like-1 (FIP1L1)-platelet-derived growth factor receptor α (PDGFRα) confers resistance to imatinib in hypereosinophilic syndrome." (PMID 36700235, 2022). "However, a PDGFRA mutation was associated with Gleevac-sensitive hypereosinophilic syndrome (HES), so perhaps decreased PDGFB-related transcription is also associated with an eosinophilic response." (PMID 20625511, 2010). "The presence of the Fip1-Like1-platelet-derived growth factor receptor alpha (FIP1L1-PDGFRα) fusion gene represents a rare cause of hypereosinophilic syndrome (HES), which is associated with organ damage." (PMID 37238279, 2023). "It is known that hypereosinophilic syndrome is associated with structural variants, including chromosome translocations, leading to gene fusions, with FIP1L1 and PDGFRA being the genes most frequently implicated." (PMID 41190063, 2025). "FIP1L1-PDGFRA is the most recurrent PDGFRA fusion gene that was first observed in patients with hypereosinophilic syndrome." (PMID 34867402, 2021). "The FIP1-like-1-platelet-derived growth factor receptor alpha (FIP1L1-PDGFRα) fusion oncogene is the driver factor in a subset of patients with hypereosinophilic syndrome (HES)/chronic eosinophilic leukemia (CEL)." (PMID 25431951, 2014). "Hypereosinophilic syndrome (HES) is a rare clinical disease that affects 0.036/100,000 patients, with a minority of patients having associated genetic markers which can encompass PDGFRA/B or FGFR1 mutations." (PMID 32617216, 2020). "The specific inhibition of PDGFRA, a receptor tyrosine kinase closely related to KIT, induced apoptosis in a hypereosinophilic syndrome (HES) cell line but did not influence on IAP expression." (PMID 27167336, 2016).
lung cancer (36 papers, 2004 to 2026). A malignant neoplasm involving the lung. "For instance, PDGFRA c.1676G>T is a non-synonymous variant reported in lung cancer (COSMIC ID 21163438; Genomic mutation identifier (COSV) COSV57273507) which is predicted to be a somatic tumor-driver mutation." (PMID 40864753, 2025). "Currently, genetic testing of KIT and PDGFRA is essential before treatment initiation, and comprehensive genomic profiling, such as for lung cancer, should be considered to identify driver mutations (e.g., SDH, BRAF, NF1, NTRK fusion, and FGFR fusion) for GISTs without KIT and PDGFRA mutations." (PMID 35965531, 2022). "Emerging evidence suggests that matrix reprogramming through dual PDGFRα/β inhibition holds potential for enhancing therapeutic outcomes in gastric and lung cancers." (PMID 40244052, 2025). "Considering additional targets, we noted that the PDGFRA 3′UTR (cDNA NM-006206) contains four predicted binding sites for the miR-141/200a and that miR-34a and -34c reportedly downregulate PDGFRA in lung cancer cells." (PMID 29305721, 2018). "For example, miR-34c inhibits lung cancer proliferation, migration and invasion by targeting PDGFRα/β; miR-34a affects the growth of pulmonary artery smooth muscle cells in human by targeting PDGFRα." (PMID 29140299, 2017). "Among them, PDGFRA was recently reported to be a direct target of miR-34a in malignant glioma, lung cancer and gastric cancer." (PMID 26214687, 2015). "PDGFRα expression in CAF is an essential factor in the progression of lung cancer and this result was partly consistent with our result." (PMID 24945657, 2014). "Besides, highly phosphorylated PDGFRA has been observed in non‒small cell lung cancer and rhabdomyosarcoma, AKT2 and AKT3 are the serine/threonine kinases that regulate cellular metabolism, cell proliferation, cell survival, cell growth and angiogenesis." (PMID 35399006, 2022). "Furthermore, TKIs increase PM localization of EGFR in lung cancers and PDGFRA/KIT in GISTs." (PMID 31484543, 2019). "In this study, the potential targets of Pinellia ternata highly overlap with lung cancer pathological genes, with FGFR4, CDK2, JAK2, KDR, PAK4, PTK2 and PDGFRA being the core." (PMID 42149884, 2026). "COL1A1, ACTA2, and alpha-SMA are relatively grouped in lung tissues, and PDGFRA, VCAM1 are expressed in both lung tissues and lung cancer cell lines, showing less specificity." (PMID 39034310, 2024). "Further in lung cancer groups, scRNA analysis showed higher expressing levels of COL1A1M COL1A2, PDGFRA and PDGFRB in identifying the CAF clusters specifically." (PMID 39034310, 2024). "The miR-34 family is down-regulated in lung cancer, leading to the up-regulation of miR-34 target genes, such as MET, BCL2, PDGFR-α (PDGFRA), and PDGFR-β (PDGFRB)." (PMID 27005669, 2016). "The markers of COL1A1, COL1A2, and FAP are significantly highly expressed in lung cancer, compared to normal tissues, while PDGFRA, PDGFRB, and ACTA2 either failed to be differentially expressed in cancer tissues, or were expressed in relative lower levels." (PMID 39034310, 2024). "In strong agreement with our previous findings, PDGFRA-mutant GISTs are confirmed as the most immunogenic GIST molecular subgroup, showing a TIS score very similar to that of tumor types known to benefit from immunotherapy (such as lung cancer)." (PMID 33806389, 2021). "Co-activation of MET, AXL, ERBB2, and EPHA2, and co-activation of DDR1 with EGFR, DDR2, HCK, PDGFRA, and FGR is evidence that simultaneous activation of multiple tyrosine kinases may be common in lung cancer." (PMID 23300999, 2013).
lung cancer (continued). "Adachi and co-workers identified a role for other receptor tyrosine kinases such as EGFR, PDGFRα (platelet-derived growth factor receptor α), and IGFR (insulin-like growth factor receptor) in the emergence of resistance to FGFR inhibitor treatment in FGFR1-amplified lung cancer." (PMID 34830951, 2021).
myeloid neoplasm (33 papers, 2012 to 2026). Proliferation of myeloid cells originating from a primitive stem cell. "Genetic testing confirmed an uncommon BCR::PDGFRA and coexisting PDGFRA mutations (c.1666G>A and c.1701A>G), confirming the diagnosis of myeloid neoplasm with BCR::PDGFRA rearrangement." (PMID 41783439, 2026). "Our patient showed an evolution from KIT mutated indolent SM to a myeloid neoplasm with PDGFRA rearrangement; when the eosinophilic component expanded, a regression of the MC counterpart was observed." (PMID 34917498, 2021). "This case describes a 57-year-old man with simultaneous diagnoses of resectable stage IIIA NSCLC and PDGFRA-rearranged myeloid neoplasm who received neoadjuvant chemotherapy and nivolumab in combination with imatinib prior to definitive resection." (PMID 40792271, 2025). "Other neoplastic myeloid conditions have been associated with monocytic abnormalities including juvenile myelomonocytic leukemia, chronic myeloid leukemia with p190 fusion, and myeloid neoplasm with rearrangements of PDGFRA, PDGFRB, FGFR1 and PCM1-JAK2." (PMID 34073699, 2021). "Here, we present a patient with indolent SM who subsequently developed a myeloid neoplasm with PDGFRA rearrangement with complete response to low-dose imatinib." (PMID 34917498, 2021). "Although some progress has been made in select subtypes of HES, including EoE and PDGFRA-positive myeloid neoplasm, generally applicable, validated biomarkers in HES are lacking." (PMID 29312946, 2017). "Cases that have either a PDGFRA or PDGFRB mutation associated with mast cell hyperplasia should be properly classified as “myeloid neoplasms with PDGFRA or PDGFRB rearrangements,” according to the World Health Organization’s classification system." (PMID 24141298, 2013). "Unfortunately, we were not able to test this hypothesis in the current study, as we could not examine EO derived from patients with FIP1L1::PDGFRA-mutated myeloid neoplasms." (PMID 38247864, 2024). "Thus, the diagnosis of myeloid neoplasm with PDGFRA rearrangement was established." (PMID 34917498, 2021). "For example, imatinib is considered a definitive treatment for patients with HES in myeloid neoplasms (usually MDS/MPNs) and FIP1L1-PDGFRA rearrangement or PDGFRA/B-re-arranged neoplasms." (PMID 34935570, 2022). "Several genetic abnormalities such as PDGFRα, PDGFRβ or FGFR1 have been observed in PDGFR-rearranged myeloid neoplasm, and the FIP1L1-PDGFRα fusion gene generated by the interstitial deletion on chromosome 4q12 has been reported to account for 5% to 15%." (PMID 24009732, 2013). "It is worth noting that a diagnosis of MPN-U cannot be made in cases with genetic lesions defining other myeloid neoplasms (BCR-ABL1 fusion, rearrangements of PDGFRA, PDGFRB, FGFR1 and/or PCM1-JAK2 fusion), if clinical data are incomplete or if biopsy samples are inadequate." (PMID 34830822, 2021).
astrocytomas (29 papers, 2008 to 2025). "Due to the lack of shared driver alterations, discrepant copy number profiles, and PDGFRA copy number gain in the recurrence, the possibility of a radiation-associated high-grade astrocytoma was considered." (PMID 37670377, 2023). "K27M-H3.1 and ACVR1 mutations as well as ALT phenotype were only found in WHO grade III–IV astrocytomas, while PIK3CA mutations and PDGFRA gains/amplifications were found in WHO grade II–IV astrocytomas." (PMID 25047029, 2014). "However, in a report of 40 patients with grade II astrocytomas and oligoastrocytomas, there was an association between high PDGFRA expression and a favourable patient outcome." (PMID 19707201, 2009). "Together with the clinical characteristics and xenograft model, we found that CNAs involving RB pathway and PDGFRA promote tumor progression in astrocytoma, IDH2-mutant." (PMID 38012788, 2023). "In TCGA IDHmut astrocytomas, PDGFRA amplification occurred more often in grade 4 tumors (21% in grade 4, 0.03% in grade 2–3, p = 0.0025, Fisher’s exact test)." (PMID 37932833, 2023). "For instance, we have demonstrated that additional “tertiary mutations”, such as PDGFRA and MYCN amplification, promoted patient tumor progression and xenograft formation in IDH1-mutant astrocytoma." (PMID 38012788, 2023). "In contrast, in grade 4 astrocytoma, only gain of PDGFRA was acquired in 3 of 8 patients, while the remaining 6 genes were newly altered in only one patient." (PMID 37741941, 2023). "The platelet-derived growth factor receptor alpha (PDGFRA) is a protein-coding gene that can reduce the growth of IDH mutant astrocytoma cells via the employment of demethylation medicines." (PMID 36146527, 2022). "PDGFRA and SOX8 were clearly more associated with OLIG1+ cells in both the oligodendroglioma and the astrocytoma." (PMID 33925547, 2021). "Activating point mutations in platelet-derived growth factor receptor alpha (PDGFRA) were present in 6/17 (35.3%) of PMMRDIA, much more often than in supratentorial, high-grade IDH-mutant astrocytomas (9.1%)." (PMID 33216206, 2021). "PDGFRA amplification was detected in 4 astrocytomas, and survival analysis showed a significant result (p = 0.043)." (PMID 34257410, 2021). "Survival analysis revealed PTEN and PDGFRA were significant prognostic factors for IDH-wild-type lower-grade astrocytoma." (PMID 34257410, 2021). "that used FISH to examine CDKN2A, CDK4, and PDGFRA copy number alterations in grade 2 and 3 astrocytomas." (PMID 33081848, 2020). "CDKN2A/B deletion was also observed in Res259 astrocytoma cells, which also contained the well-described 4q12 amplicon, resulting in high level gains of the oncogenes PDGFRA and KIT, and low-level gain of a region including KDR/VEGFR2." (PMID 19365568, 2009). "Even when considering generally higher PDGFRA expression in IDHmut astrocytomas than in IDHwt GBs, only a subpopulation of tumors with gene amplification represented outlier expression levels (in IDHmut astrocytomas, four tumors with PDGFRA amplification, three of which were grade 4)." (PMID 37932833, 2023). "In the present study, a correlation between PDGFRA gain/amplification and CDKN2A homozygous loss was seen, and might imply that astrocytoma with alteration of PDGFR is associated with “RTK I” GBM." (PMID 34257410, 2021). "However, segmental amplifications of 4q including PDGFRA, often associated with a concomitant loss of larger parts of 4q, were observed with a similar frequency in PMMRDIA (30%) and conventional supratentorial IDH-mutant high-grade astrocytomas (35%)." (PMID 33216206, 2021). "Importantly, we observed that the tumor cells in the center zone displayed a prominent enrichment of stem cell markers Sox2 and Sox9, but did not express differentiated cell markers Olig2, CC1, S100β, and PDGFRα as observed in oligodendrocytoma and/or astrocytoma." (PMID 33863883, 2021).